RN7SL156P (RNA, 7SL, cytoplasmic 156, pseudogene)
Gene: Miscellaneous RNA gene on chromosome 20 (36,870,099 to 36,870,402, forward strand). Ensembl gene ENSG00000242509.
Homologues: Orthologues: chimpanzee Metazoa_SRP (98% identical), macaque Metazoa_SRP (93% identical). Paralogues in human: RN7SL234P (76% identical), RN7SL33P (76% identical), RN7SL268P (75% identical), RN7SL526P (72% identical), RN7SL317P (72% identical), Metazoa_SRP (71% identical), RN7SL40P (71% identical), Metazoa_SRP (69% identical), RN7SL1 (69% identical), RN7SL2 (69% identical), RN7SL5P (69% identical), RN7SL775P (69% identical), and 702 more.